STAT3 (signal transducer and activator of transcription 3)
Diseases named in the same sentence as STAT3 in open-access papers (continued):
Sharing a sentence is not in itself a finding about the gene and the disease.
lung carcinoma (continued). "Notably, inhibiting CXCL12 signaling and the STAT3 pathway reduced the conversion of NFs to CAFs, thereby hindering lung cancer progression progression both in vitro and in vivo." (PMID 40199862, 2025). "Our previous study highlighted the anticancer potential of sea hare hydrolysate (SHH), particularly its role in regulating macrophage polarization and inducing pyroptotic death in lung cancer cells through the inhibition of signal transducer and activator of transcription 3 (STAT3)." (PMID 39803276, 2025). "STAT3 activation may be a critical target in CAF-induced osimertinib resistance in lung cancer cells." (PMID 40703348, 2025). "For example, disrupting EML4-ALK LLPS and impairing STAT3 phosphorylation may be a novel treatment for EML4-ALK-positive lung cancer." (PMID 40642070, 2025). "Importantly, we demonstrate that Cyclin Y interacts with Chk1 to positively modulate the expression of RRM2 and activate STAT3 signaling, ultimately promoting radioresistance in lung cancer." (PMID 40083692, 2025). "Furthermore, western blotting and flow cytometric analyses indicated that panduratin A induces apoptosis by inhibiting p-EGFR and its downstream effectors, p-STAT3 and p-Akt, in lung cancer cells." (PMID 40076971, 2025). "Therefore, inhibition of the CXCL12/STAT3 axis is a promising strategy for the treatment of lung cancers and other CXCL12-dependent malignancies." (PMID 40199862, 2025). "Studies were conducted on different lung cancer cell lines, including H1975 cells, in which ethanol extract of Scutellaria baicalensis and triterpenes extracted from H. diffusa effectively induced apoptosis by inactivating STAT3 in EGFR-TK-resistant cells." (PMID 40365309, 2025). "Furthermore, silibinin modulates lung cancer (H3122 and H2228) cells by enhancing the therapeutic effects of nintedanib, brigatinib, and lorlatinib through the inhibition of STAT3 activity." (PMID 40490812, 2025). "Similarly, in lung cancer, afatinib-induced STAT3 activation reduces drug sensitivity, which can be reversed by inhibiting IL-6R/JAK1/STAT3 signaling." (PMID 40999385, 2025). "Hence, direct clinical evidence supporting the efficacy and safety of CUR and RES as STAT3 modulators in lung cancer patients remains insufficient." (PMID 40860906, 2025). "Constitutively active or hyperactive STAT3 is found in many lung cancers." (PMID 41380973, 2025). "Notably, JAK2, STAT3, and PD-L1 protein expression was significantly lower in lung cancer tissues of mice in the IFN-γ + BMSCs + QSFZYL group compared to the BMSCs, QSFZYL, and IFN-γ + BMSCs groups (P< 0.05)." (PMID 40642092, 2025). "Notably, previous studies conducted in xenografted colorectal and lung cancer cell lines have suggested that JAK/STAT3 blockade preserves fat by inhibiting lipolysis." (PMID 41278737, 2025). "Our study reveals CAFs could promote the conversion of NFs to CAFs-like cells through the CXCL12/STAT3 axis, enhancing tumor growth and metastasis in lung cancer." (PMID 40199862, 2025). "In this study, western blotting and flow cytometric analyses indicated that panduratin A induces apoptosis by inhibiting phosphorylated EGFR (p-EGFR) and its downstream effectors, phosphorylated STAT3 (p-STAT3) and phosphorylated Akt (p-Akt), in both A549 and H1975 lung cancer cell lines." (PMID 40076971, 2025). "However, the precise mechanisms responsible for continuous STAT3 activation in lung cancers are poorly understood." (PMID 39985075, 2025). "Additionally, IL-11 facilitates lung cancer cell chemoresistance via the IL-11R/STAT3 signaling pathway, which promotes the activation of anti-apoptotic proteins." (PMID 40426949, 2025). "TIPE3 enhances the progression of lung cancer by activating Akt/mTOR, NF-κB, and STAT-3 signaling." (PMID 40280943, 2025).
lung carcinoma (continued). "Potential upstream activators of STAT3 in lung cancer include IL-6, which has been reported to be constitutively produced in some lung cancer cell lines and lung cancer patients, and EGFR, which is often overexpressed or mutated in the kinase domain in NSCLC cells." (PMID 41380973, 2025). "18β-Glycyrrhetinic acid significantly impacts intracellular mechanisms such as increasing levels of reactive oxygen species (ROS) and regulating signaling pathways like MAPK, STAT3, and NF-κB which are crucial for managing the proliferation and metastasis of lung cancer cells." (PMID 40129771, 2025). "Based on this, targeting the p-STAT3/PD-L1 pathway in lung cancer treatment may benefit cancer patients by enhancing antitumor immunity." (PMID 39811730, 2024). "STAT3 is significantly activated in lung cancer and is essential in driving tumor advancement." (PMID 39811730, 2024). "This gene has also been proposed as a potential biomarker for lung cancer after finding that it interacts with STAT3 in lung cancer cells, regulating IL-6 and thus mediating inflammatory processes, while another study determined that its blockade inhibited lung cancer cell growth." (PMID 39361370, 2024). "miR-210-3p regulates STAT3 signaling in lung cancer to mediate EMT and metastasis." (PMID 39409003, 2024). "On the other hand, JAK1 is responsible for STAT3 activation in lung cancer cells." (PMID 39770330, 2024). "In A549 and H460 lung cancer cells, UA was explicitly recognized as suppressing STAT3 activity." (PMID 38397437, 2024). "Additionally, phosphorylation of PKM2 along with STAT3 inhibition has been shown to impede lung cancer cell proliferation effectively." (PMID 39070142, 2024). "In summary, these findings suggest that ACC1 may serve as an effector of STAT3 in the regulation of lipid metabolism in lung cancer." (PMID 38495496, 2024). "In addition, existing studies have documented the upregulation of STAT3 in breast and lung cancers, which can be restricted by miR-125a-5p8." (PMID 39132168, 2024). "But the combined evaluation of mTOR and STAT3 genes suggested that these also could be used as a critical gene set for predicting lung cancer patient outcomes." (PMID 38886756, 2024). "Meanwhile, STAT3 activation in B cells promotes the angiogenesis in melanoma and lung cancer." (PMID 38245798, 2024). "For instance, targeting intracellular STAT3 with napabucasin, a drug clinically approved for treating gastric cancer and under clinical trials for more aggressive malignancies, has also shown promise in alleviating lung cancer BM." (PMID 39512767, 2024). "Notably, a regimen of dual inhibition of HOXC10 and STAT3 is established to improve the effectiveness of HOXC10 inhibition alone in KRAS-mutant lung cancer bone metastasis." (PMID 39191757, 2024). "Interestingly, lung cancers in turn activated a STAT3/PD-L1 axis that facilitated the polarization of TANs towards the N2 phenotype demonstrating crosstalk between the cancer cells and TANs." (PMID 38765006, 2024). "Likewise, the authors showed that miR-526b-3p mediates anti-tumor effects and that its inhibition was neutralized with Avelumab treatment, indicating that PD-L1 is a downstream target of miR-526b-3p/STAT3 in lung cancer." (PMID 39343796, 2024). "Furthermore, STAT3 expresses ~1.45 fold higher in CDDP-resistant lung cancer cell lines than CDDP-sensitive lung cancer cell lines." (PMID 39343796, 2024). "Furthermore, CUR effectively downregulated EGFR and STAT3 expression in lung cancer cells, suggesting its potential to disrupt key signaling pathways involved in tumor progression." (PMID 39508791, 2024). "In addition, we identified that senescent tumor cells up-regulate macrophage CD73 expression via the SASP-IL-6-JAK/STAT3 signaling pathway, and validated this in lung cancer clinical specimens and databases." (PMID 38323313, 2024).
lung carcinoma (continued). "IL-1β and IL-6 can induce EMT in breast cancer cells via the STAT3 pathway and promote angiogenesis, which suggests that BMAs may similarly exacerbate bone destruction in lung cancer bone metastasis." (PMID 38571500, 2024). "A recent study reported that elevated STAT3 levels affected gemcitabine resistance in lung cancer." (PMID 38555280, 2024). "Notably, STAT3 activation in lung cancer orchestrates immunosuppressive characteristics by inhibiting T cell-mediated cytotoxicity." (PMID 39514276, 2024). "The current study aimed to determine how effectively lung cancer cells (A549) might be prevented from growing by blocking the STAT3 and FAK intervention signaling pathways." (PMID 39588118, 2024). "To examine whether FBNAF inhibits STAT3 phosphorylation (Tyr705), we performed western blotting using human A549 lung cancer cells, which highly express STAT3." (PMID 38834900, 2024). "Normal STAT3 signaling is tightly controlled in standard cellular responses, but constitutive STAT3 activation often occurs in a variety of human cancers, especially lung cancer." (PMID 39085755, 2024). "STAT3 activation has been observed in hematological malignancies and solid tumors, head and neck cancer, melanoma, lung cancer, pancreatic cancer, breast cancer, prostate cancer, and ovarian cancer." (PMID 38834900, 2024). "The JAK/STAT3 pathway is also hyperactivated in lung cancer which serves as a link thereof." (PMID 39770330, 2024). "RECK suppression via the STAT3/miR-92a axis promotes the invasiveness of lung cancer cells." (PMID 38495494, 2024). "Studies indicate that the interaction between MPC1 and mitochondrial STAT3 (mito-STAT3) disrupts the distribution of STAT3, reduces the activity of cytoplasmic STAT3 (cyto-STAT3), and promotes the malignant progression of lung cancer, including invasion and metastasis." (PMID 39179991, 2024). "In breast and lung cancers, butein also downregulates STAT3 phosphorylation." (PMID 38686052, 2024). "Building on the concept of targeted gene silencing, cationic solid lipid nanoparticles containing plasmid DNA designed for STAT3 downregulation (cSLN/plasmid DNA complexes) were developed to deliver RNA interference molecules targeting STAT3 in resistant lung cancer cells." (PMID 38794306, 2024). "Interestingly, IL-6 has been greatly upregulated in lung cancer, and a molecular link has been suggested via the transcription factor signal transducer and activator of transcription 3 (STAT3) pathway." (PMID 38103126, 2024). "Interestingly, in lung cancer cells, STAT3 transcriptional activity can be activated to promote Visfatin expression, thereby initiating the development of cisplatin resistance." (PMID 39452130, 2024). "In addition, some studies have indicated that FGF2 regulates angiogenesis through the JAK2/STAT3 signaling pathways in both lung cancer and melanoma." (PMID 39075612, 2024). "In addition, STAT3 has been found to have an effect of resisting various tumors and inhibiting cell proliferation and invasion, such as lung cancer, thyroid cancer, gastric cancer, and so on." (PMID 39691419, 2024). "The transcription factor STAT3 (signal transducer and activator transcription 3) is kept constitutively expressed and could be related to the tumorigenesis of lung cancer." (PMID 38136991, 2023). "JAK2/STAT3 signaling pathway is widely demonstrated to highly abnormally activate in various cancers, for example, pancreatic cancer, gastric cancer, breast cancer, liver cancer, colorectal cancer, colon cancer, ovarian cancer, lung cancer." (PMID 37716993, 2023). "Additionally, it has been clearly shown that IL-6 plays an essential role in lung cancer promotion, and its blockade significantly inhibits lung cancer development, STAT3 activation in tumor cells, tumor cell proliferation, and angiogenesis markers." (PMID 37894302, 2023).
lung carcinoma (continued). "Using a large panel of lung cancer cell lines, we identified a set of “antioxidant-capacity” biomarkers (ACB), which were tightly repressed, partly by STAT3 and STAT5A/B in sensitive cells, rendering them susceptible to multiple redox-targeting and ferroptosis-inducing drugs." (PMID 36958250, 2023). "In addition, the cytotoxicity of these compounds was shown, which AB posed the most potent toxic to lung cancer cells, and STAT3 was validated as a potential target of this compound." (PMID 36707691, 2023). "Our work reveals that FIBP modulates the STAT3/EME1 axis to drive lung cancer progression and radioresistance, indicating that targeting FIBP may be a novel intervention strategy for lung adenocarcinoma radiotherapy." (PMID 37564211, 2023). "In addition, bioinformatics analysis revealed that cell cycle regulators, such as cyclin D1 and STAT3, are targets of let-7c, and overexpression of these genes leads to cisplatin resistance in lung cancer cells." (PMID 36778005, 2023). "When UA was applied to the cisplatin-resistant cells, levels of the pluripotent stem cell transcription factors were restrained by the inhibition of the Jak2/Stat3 signaling pathway, which reduced the enrichment of tumor stem cells, and in turn, reversed cisplatin resistance in lung cancer cells." (PMID 37089712, 2023). "In addition, the results of Western blots showed that phosphorylation of JAK2 and STAT3 protein was inhibited by the treatment of exogenous rhTβ4 in both a lung cancer cell line and a lung fibroblasts cell line in vitro." (PMID 36835236, 2023). "In marked contrast, in lung cancer cells, STAT3 was identified as crucial for galvanotaxis." (PMID 37508461, 2023). "In addition, Zhang colleagues found that ginseng Rh4 inhibited the expression of JAK2, STAT3, and p-STAT3, which inhibited the growth and metastasis of lung cancer." (PMID 38202610, 2023). "Interestingly, it was demonstrated that IL-6 blockade significantly inhibited lung cancer promotion, tumour cell-intrinsic STAT3 activation, tumour cell proliferation, and angiogenesis markers." (PMID 37569672, 2023). "Some studies suggest OSM may repress lung cancer growth, but can promote lung cancer metastasis via activation of STAT3 and STAT5, thus increasing expression of tumorigenic factors such as tissue type plasminogen activator (tPA)." (PMID 37841259, 2023). "Currently, there are no studies demonstrating a direct relationship between MTDH and STAT3, but a recent study showed that treating lung cancer cells with a mushroom extract decreased the expression of both MTDH and STAT3, inhibiting proliferation and metastasis." (PMID 36902125, 2023). "In addition, it has been reported that IL-17 promotes lung cancer invasion and proliferation through the STAT3 pathway." (PMID 37894738, 2023). "Napabucasin, an inhibitor of intracellular STAT3, could remit bone metastases of lung cancer and was approved for the treatment of gastric cancer." (PMID 36755257, 2023). "Notably, ectotrophic expression of both IRF1 and STAT3 largely restored IFN-γ–induced PD-L1 expression in ATXN3-null lung cancer cells." (PMID 38038129, 2023). "inhibits lung cancer cells by regulating the IL-6-induced JAK2/STAT3 pathway." (PMID 37291549, 2023). "STAT3-related anoikis-resistance has been reported in cancer cells of human pancreatic cancer, melanoma, cholangiocarinoma, esophageal squamous cell carcinoma, squamous cell carcinoma, nasopharyngeal carcinoma, and lung carcinoma." (PMID 36902166, 2023). "We show here that PA induces the rapid phosphorylation of STAT3 in the lung cancer cells." (PMID 37509443, 2023). "In addition, enhanced activation of STAT3 was reported to promote cancer cell stemness and the immune evasion of lung cancers." (PMID 38137415, 2023). "Indeed, DDIAS inhibits PTPRM/STAT3 binding and STAT3 Y705 dephosphorylation, allowing STAT3 activation to persist in lung cancer." (PMID 37121974, 2023).
lung carcinoma (continued). "Moreover, the silencing of STAT3 by shRNA in combination with cisplatin increased apoptosis and the caspase-3 activity in lung cancer cells compared with treatment with cisplatin alone." (PMID 38067351, 2023). "Moreover, TSLNC8 exhibited a remarkable ability to inhibit the aggressive behaviors of lung cancer cells by targeting the IL-6/STAT3/HIF-1a signaling pathway." (PMID 37781073, 2023). "Network analysis and metabolomics combined with western blot demonstrated that GYP might exert anti-lung cancer effects as well as enhance the pharmacological effects of the chemotherapeutic agent cisplatin through the MAPK14/STAT3 signaling pathway." (PMID 36532716, 2022). "In addition to chemotherapeutic drugs and EGFR-TKI inhibitors, the combination of STAT3 inhibitors and other small molecular inhibitors has also achieved promising therapeutic effects on lung cancer." (PMID 36559280, 2022). "In summary, we confirmed that STAT3/FOXM1/ATG7 signalling might be essential for autophagy induced by icotinib in resistant lung cancer cells." (PMID 35690866, 2022). "The JAK/STAT3 signaling pathway in lung cancer cells is regulated by TGF-β." (PMID 36591515, 2022). "Moreover, we show that SH2B3 binds to JAK2 to inhibit JAK2/STAT3 signaling, supporting that hyperactivity of JAK2/STAT3 signaling in lung cancer cells results from diminished SH2B3 expression level." (PMID 35589677, 2022). "Moreover, work by Bivona and colleagues has shown that genetic activation of STAT3 partially rescued ALK-rearranged lung cancer cells from the effects of ALK inhibitor treatment, with greater dependence on the RAS-MAPK pathway." (PMID 35228642, 2022). "In the present study, we used CCK assay and flow cytometry analysis and these data indicated that combination with IFNγ and STAT3 inhibitor could promote apoptosis and inhibit cell cycle transition to inhibit the proliferation of lung cancer cells." (PMID 36185620, 2022). "Thus, targeting the STAT3 signaling pathway has emerged as a promising therapeutic strategy for lung cancers." (PMID 36559280, 2022). "Yu and colleagues elucidated that enriching circHIPK3 facilitated the expression of sphingosine kinase 1 (SphK1), cyclin-dependent kinase 4 (CDK4), and signal transducer and activator of transcription 3 (STAT3) through impeding miR-124 in lung cancer cells, and accelerating LC cell growth." (PMID 36292157, 2022). "Among the seven STATs, STAT3 signaling activation contributes to the progression of cancers, while inhibition of STAT3 signaling leads to apoptosis of various cancer cells including lung cancer." (PMID 36005200, 2022). "Targeting intracellular STAT3 with napabucasin can also remit lung cancer bone metastasis." (PMID 36006737, 2022). "For instance, the two most classical pathways involved in inflammation of NF-κB and STAT3 could promote lung cancer cell proliferation when activated." (PMID 36188592, 2022). "This study illustrated that STAT3 mediates treatment-induced adaptive survival of ALK-rearranged lung cancer cells through transcriptional regulation of apoptosis, identifying STAT3 as a promising therapeutic target of the combination therapy aimed at tumor eradication." (PMID 35228642, 2022). "In nearly 50% of lung cancers, STAT3 can be activated by different upstream phosphokinases." (PMID 35506290, 2022). "Therefore, STAT3 mediates adaptive survival of ALK-rearranged lung cancer cells through evasion of apoptosis." (PMID 35228642, 2022). "Feedback activation of STAT3 in oncogene-addicted cancers has also been demonstrated with other targeted therapies, implicating a potential role of targeting these pathways more broadly in the genomic subtypes of lung cancer." (PMID 34773474, 2022). "In vitro work suggests that STAT3 CAF signaling can enhance the metastatic potential of lung cancer cells, and IL-11/STAT3 signaling may play a role in cisplatin chemoresistance." (PMID 35406557, 2022).